CGAS (cyclic GMP-AMP synthase)
Diseases named in the same sentence as CGAS in open-access papers (continued):
Sharing a sentence is not in itself a finding about the gene and the disease.
tumor (continued). "In this study, we comprehensively analyzed the expression pattern, prognostic value of the cGAS-STING pathway, as well as its correlation with TIICs in the tumor microenvironment in an extensive manner." (PMID 35983076, 2022). "Micronuclei and mtDNA are detected by cyclic GMP-AMP synthase (cGAS) and stimulate production of type I IFN as well as other inflammatory cytokines via the STING pathway, thereby triggering anti-tumor immune responses by CD8+ T cells." (PMID 36230796, 2022). "Our results show that STING and cGAS expression is often markedly reduced or abolished in SCLC cell lines and tumours, thus impairing the activity of the STING pathway and the activation of immune genes." (PMID 35794238, 2022). "In a mouse model of ovarian cancer, the SETDB1-TRIM28 complex inhibited the formation of micronuclei in the cytoplasm, thereby inhibiting the activity of the cGAS-STING pathway and suppressing anti-tumor immunity." (PMID 36353640, 2022). "Recent studies found the cGAS-STING signaling cascade is involved in anticancer immune responses and cancer immune escape, which plays dichotomous effects on tumor development." (PMID 35209954, 2022). "In mouse models, the nuclear paraspeckle assembly transcript 1 inhibits the cGAS-STING signaling and cytotoxic T cell infiltration into the tumor microenvironment, thereby promoting tumor growth." (PMID 36359370, 2022). "However, tumor-associated macrophages (TAM; or M2-like) can shift towards their classic pro-inflammatory phenotype (M1-like) via type-I IFN responses and activation of the cGAS/stimulator of interferon genes (STING) pathway, which is critical for initiating anticancer immune responses." (PMID 35347108, 2022). "The cGAS-STING signaling pathway has a dichotomous role in cancer, with both autonomous and involuntary antitumor effects in tumor cells." (PMID 36467504, 2022). "Previous studies demonstrated that the expression of cGAS and STING, as well as their function in the cancer cells, were essential for optimal anti‐tumour T cell induction by radiotherapy." (PMID 35415876, 2022). "The cGAS–STING-mediated interferon production can also be induced by the direct interaction of APCs and tumor cells." (PMID 35869062, 2022). "When the cGAS-STING pathway in tumor cells is activated, cytokines such as IL-6 and type I IFN are induced, leading to tumor cell apoptosis or death." (PMID 35889509, 2022). "In this review, we introduce the cGAS-STING signaling pathway and its effect in tumor immunity and discuss the recent strategies of activation of the STING signaling pathway and its research progress in tumor immunotherapy." (PMID 35889509, 2022). "Collectively, SOX2 upregulation dampened intrinsic host immune activation of cGAS /STING signalling, and inhibited IR‐induced anti‐tumour immune responses." (PMID 35415876, 2022). "For example, ATM (ataxia telangiectasia mutated) inhibition promotes mtDNA leakage into the cytoplasm to activate cGAS-STING signaling and enhance lymphocyte infiltration into the tumor microenvironment." (PMID 35002511, 2022). "Cytoplasmic DNA produced by irradiated tumor cells is sensed by cGAS, which enhances the expression of type I IFNs through cGAS-STING signaling in host immune cells and tumor cells." (PMID 36532071, 2022). "Conversely, CSG-4 shows lower expression of the response genes suggesting activation of the cGAS-STING pathway but failure to activate the downstream IFN signaling cascade designed to produce IFNs and attract tumor-infiltrating Leukocytes (TIL)." (PMID 36923311, 2022). "As one example, it was recently shown that PARPi leads to DNA damage that triggers the cGAS/STING pathway, type I interferon signaling, and then cytotoxic T cell function; resulting in tumor clearance." (PMID 35538088, 2022). "Inhibition of PCAT1/SOX2 enhanced IR‐induced cGAS/STING activation and anti‐tumour immune responses." (PMID 35415876, 2022).
tumor (continued). "The results of IHC exhibited that the expression of CD3, CD8, cGAS and STING were reduced in SOX2‐expressing tumours." (PMID 35415876, 2022). "Nuclear and mitochondrial DNA are easily damaged in tumor cells, inducing IFN-I through the cGAS–STING–IRF3-dependent pathway." (PMID 36683857, 2022). "When cGAS recognizes pathogen DNA in the cytoplasm of cells, the cGAS–STING signaling pathway is activated and plays an important role in host defense against pathogen infection and tumor development." (PMID 35536585, 2022). "Recently, special attention has been paid to emphasizing and critically discussing the cGAS-STING pathway, which is a dominant pathway that responds to cytosolic DNA in the context of tumor immunity, cellular senescence, and inflammatory diseases." (PMID 35979145, 2022). "Our results demonstrated that cGAS-STING-expressing tumors displayed elevated markers of tumor-suppressive CAFs, as well as strong infiltration of anti-tumor immune cells in the stromal component of the tissues." (PMID 35773436, 2022). "Radiation-induced DNA damage can trigger the cGAS-STING pathway and induce T cell responses, and the combination of radiotherapy with STING agonists produces a better synergistic anti-tumor effect." (PMID 35889509, 2022). "The cyclic GMP-AMP synthase (cGAS)-STING pathway is an important mechanism to protect cells from cytoplasmic DNA damage, and the anti-tumor efficacy of PARP inhibition depends on the activation of the STING pathway." (PMID 35906622, 2022). "In human colon carcinoma, melanoma, glioma, and hepatoma cell lines, tumor cells can evolve strategies to inhibit the activation of the cGAS–STING signaling pathway and reduce the production of IFN-β, which is conducive to the survival of tumor cells." (PMID 35536585, 2022). "Cytosolic DNA is prevalent in cells constituting the tumor microenvironment (TME) and can activate the cyclic guanosine monophosphate–adenosine monophosphate synthase (cGAS)–stimulator of interferon genes (STING) innate immune pathway." (PMID 35325182, 2022). "Activation of cGAS-STING signals has recently been confirmed to have direct cytotoxic effects on some tumor cells, inducing immunogenic death of tumor cells." (PMID 35748951, 2022). "In contrast, appropriate activation of the cGAS-STING pathway can exhibit potential therapeutic effects in some cancers, and STING agonists can enhance anti-tumor activity." (PMID 36297353, 2022). "For example, cGAS-STING signaling and antitumor immunity are important determinants of the tumor response to taxol, PARP inhibitors, and radiation." (PMID 36003402, 2022). "Similar to cancer regulation of the cGAS-STING pathway with EVs from surrounding cells, the cGAS-STING pathway inside the surrounding cells also contributes to tumor homeostasis." (PMID 35741087, 2022). "The release of mtDNA as a result of mitochondrial damage stimulates TLRs, cGAS, and STING, activating various inflammatory pathways and exacerbating tumor progression." (PMID 36499214, 2022). "We constructed a cGAS-STING gene signature to predict survival and tumor immunity across human cancers, which can serve as a novel prognostic indicator and therapeutic target, especially in KIRC and KIRP." (PMID 35983076, 2022). "Current studies have shown that cGAS-STING signaling is activated in highly aggressive tumors and is closely involved in tumor progression." (PMID 35692503, 2022). "The cGAS-STING pathway is a key regulator of innate immune sensing of cancer, with a strong potential to enhance tumor rejection through the induction of adaptive immune responses mediated predominantly by type I interferons." (PMID 35595822, 2022). "SOX2 silencing augmented CD8+ T cells in tumours, and CD8+ T cells declined in part after the addition of cGAS inhibitor RU.521." (PMID 35415876, 2022).
tumor (continued). "cGAS-STING pathway mediates tumor immunity for immune surveillance and clearance and seems to exert tumor suppressive effects in cancer related therapies such as radiation therapy, chemotherapy and immunotherapy." (PMID 36588690, 2022). "In the present study, we found that triple therapy further activated cGAS/STING signaling, increased CD8+ T cell proliferation and enhanced the immune memory activation that facilitated tumor regression and durable control." (PMID 36443299, 2022). "When the dsDNA of tumor cells enters normal cells, it can be promptly sensed and detected by cyclic guanosine monophosphate (GMP)-adenosine monophosphate (AMP) synthase (cGAS)." (PMID 35806118, 2022). "Shannon Grabosch’s study demonstrated that cisplatin activated the cGAS-STING pathway to modify tumor immunogenicity by increasing PD-L1, MHC I and calreticulin in tumor cells." (PMID 35720348, 2022). "Activated cGAS‐STING pathway and type I IFN signal were essential for tumour‐specific T‐cell cross‐priming and the whole cancer‐immunity cycle." (PMID 35415876, 2022). "G3BP1 deletion disrupts the cGAS pathway and blocks the expression of SASP factors, and these SASPless senescent cells disrupt senescence-mediated cancer cell growth in vitro and tumor growth in vivo." (PMID 36330442, 2022). "Usually, activation of the cGAS-STING pathway is sufficient to recruit effector T cells into the tumor microenvironment and eliminate the tumor cells." (PMID 35978045, 2022). "Tumor-derived DNA induced by radiation therapy can activate the cGAS-STING pathway to result in the production of type I IFNs, maturation of dendritic cells (DCs), and triggering CD8+ T cells to eliminate tumor cells." (PMID 35978045, 2022). "To study the role of cGAS-STING signaling pathway in the nanoassembly-mediated immunotherapeutic effect, we established B16F10-tumor-bearing STING-knockout (STING-KO) C57 mouse models and comparatively analyzed their response to BSA-Man@Mn2+-Ft@Lap treatment." (PMID 36167857, 2022). "Recently, the cGAS-STING pathways have also been reported to be involved in cellular senescence, anti-tumor immunity and various autoimmune and autoinflammatory syndromes." (PMID 35973990, 2022). "Meanwhile, cGAS can recognize tumor cell DNA and produce large amounts of IFN-β, which in turn enhances antitumor immunity to control tumor development." (PMID 35536585, 2022). "Combination therapy of LGG and anti-PD-1 mechanically increases tumor-infiltrating DCs and IFN-β induction through the cGAS-STING-IRF7 cascade." (PMID 35292881, 2022). "Meanwhile, cGAS-STING-mediated DNA sensing has been reported that maintains CD8+ T cell stemness and promotes anti-tumor T cell therapy." (PMID 35979145, 2022). "It has been described that both chemotherapeutic agents (e.g. cisplatin and etoposide) and radiotherapy induce DNA damage, which can activate the cGAS-STING pathway promoting immune responses and enhancing tumor cell death." (PMID 35251003, 2022). "In this study, we for the first time analyzed the relationship between overall expression level of cGAS-STING signaling pathway and tumor prognosis." (PMID 35983076, 2022). "DNA damage via ionizing radiation and certain chemotherapies triggers cGAS/STING and the production of pro-inflammatory cytokines necessary for immune cell recruitment and tumor clearance." (PMID 36059473, 2022). "Our research indicated that Bio-MnO2 NPs plus RT activated strong immune responses via the cGAS/STING pathway and ICD, further supporting infiltration of immune cells especially CTLs, killing tumor cells while converting immunosuppressive microenvironment." (PMID 36144927, 2022). "Expression of the cGAS-STING pathway at both the protein and RNA levels was increased in a dose-dependent pattern in DCs cocultured with cuproptosis-activated tumor cells." (PMID 36581992, 2022).
tumor (continued). "Meanwhile, increasing evidence indicate that the cGAS-STING pathway is involved in tumor promotion and metastasis and its chronic activation can induce immunosuppressive tumor microenvironment." (PMID 35692503, 2022). "STING agonists utilize the principle of cGAS-STING-induced type I interferon response and are now commonly used in clinical practice as one of the anti-tumor treatments." (PMID 36545321, 2022). "Consistent with this notion, the cGAS-STING pathway is frequently inactivated in tumors, and tumor cells are often unable to induce type I interferon signaling by transfected cGAMP or dsDNA." (PMID 36003402, 2022). "The STING pathway is indispensable in tumor treatment, as activation of STING has a synergizing effect on therapy in pancreatic cancer, whereas knockdown of STING or cGAS signaling is sufficient to abolish the efficacy of immune checkpoint inhibitors." (PMID 35501802, 2022). "To determine the potential therapeutic contribution of cGAS-STING signaling pathway in the nanoagonist-mediated antitumor effects, we have comprehensively studied the responses of splenic immune cells to tumor-derived DAMPs through comparative analysis." (PMID 36167857, 2022). "cGAS/STING-mediated IFN signaling enhances the infiltration of anti-tumor T cells and NK cells into the tumor." (PMID 36276148, 2022). "Meanwhile, when DDR is absent, the damaged DNA enters the cytoplasm and activates the CGAS-STING signaling pathway, which is related to the activation of innate immunity and CD8+ cytotoxic T cells and mediates tumor immunity." (PMID 36478716, 2022). "It is suggested that the progress of pcna Y211 phosphorylation in nuclear DNA replication is related to the DNA sensing cascade initiated by cGAS (cyclic GMP-AMP synthase) in the cytoplasm, thus regulating immune surveillance to inhibit tumor metastasis." (PMID 35689249, 2022). "cGAS initiates a signaling cascade, triggering STING activation and interferon production by tumor cells and dendritic cells, ultimately supporting anti-tumor T cell recruitment." (PMID 34572943, 2021). "Remarkably, the cGAS/STING pathway, initially involved in tumor cell clearance has also been shown to act as a pro-survival pathway in metastases." (PMID 35008251, 2021). "BCG intratumoral treatment in cGAS−/− and STING−/− mice presents similar results as C57BL/6 WT animals, discarding the importance of this pathway in BCG tumor treatment." (PMID 34341449, 2021). "Then by inducing senescence in cells failing successful metastasis, the cGAS/STING pathway influences and primes the tumor microenvironment." (PMID 35008251, 2021). "TREX1 is the gatekeeper enzyme of the cGAS-STING pathway, and tumor-derived DNA generated spontaneously or induced by radiotherapy or chemotherapy can be degraded by TREX1." (PMID 33868310, 2021). "They showed that the activation of cGAS, STING, and interferon regulatory factor 3 (IRF3) was tumor-DNA-dependent and contributed positively to dendritic cell activation." (PMID 34072037, 2021). "It was later shown that tumor cells transfer cGAMP to astrocytes through these gap junctions, resulting in astrocyte cGAS-STING-mediated IRF activation, and subsequent secretion of tumor-supportive IFN-α, TNF, and TGF-α." (PMID 34716900, 2021). "Previously, it has been reported that silencing cGAS decrease the viability of BT-549 cells; furthermore, our xenograft experiment in BALB/nu mice also demonstrated a decrease in tumor growth in sh-cGAS MKN45 cells." (PMID 37305397, 2021). "In myeloid cells, cGAMP agonists can activate their cGAS-STING signaling pathway, thereby promoting their killing of tumor cells." (PMID 35046953, 2021). "Ablation of cGAS and STING prevented the activation of spontaneous anti-tumor immune responses, and suppressed the immunogenic potential of cytotoxic treatments such as radiotherapy and chemotherapy." (PMID 33717156, 2021).
tumor (continued). "In this study, we explored the correlation between the cGAS-STING pathway and the tumor microenvironment in OSCC patients." (PMID 34625078, 2021). "Downregulation of cGAS and STING was observed in clinically advanced tumors, indicating a possible tumor-driven escape mechanism from immunosurveillance." (PMID 34381458, 2021). "In summary, we investigated the correlation between cGAS-STING signaling pathway and the tumor immune microenvironment in OSCC patients." (PMID 34625078, 2021). "We firstly found higher score of macrophage regulation, lymphocyte infiltration, and IFN-gamma response in the cGAS-STING high cluster, which indicated the correlation between cGAS-STING activation and macrophages, lymphocytes in the tumor microenvironment." (PMID 34625078, 2021). "Accordingly, cGAS activation and IFN-I signaling in DCs are required for anti-tumor immune responses after radiotherapy." (PMID 34925363, 2021). "The cGAS-STING-mediated inflammatory response can promote tumorigenesis and metastasis in a tumor-type-dependent and stage-specific manner." (PMID 33968056, 2021). "Several studies have shown that micronuclei (or cytosolic DNA)-dependent cGAS/STING activation transduces IFNα/β signaling in cancer cells, resulting in the upregulation of PD-L1 in tumor microenvironments." (PMID 34196706, 2021). "Stimulation of the cGAS-STING signaling pathway increased type I IFNs and tumor-infiltrating lymphocytes (TILs) levels to trigger an immunogenic response." (PMID 33843442, 2021). "More importantly, errors in chromosome separation spills DNA into the cytosol, leading to activation of the cGAS‐STING cytosolic DNA‐sensing pathway and therefore promoting tumour invasion and metastasis." (PMID 34013637, 2021). "In recent years, a large number of studies have reported a connection between the cGAS-STING signaling pathway and anti-tumor immunity, cancer progression, the tumor microenvironment, and pharmacological strategies for cancer treatment." (PMID 34386500, 2021). "Besides, Neurofibromin 2 (NF2/Merlin/schwannomin) is a classical tumor suppressor and naturally occurring mutations in the FERM domain could transform it into a profound suppressor, which can inhibit the cGAS-STING pathway by blocking STING-mediated DNA sensing." (PMID 35046953, 2021). "We discuss the effects of radiotherapy on immunogenic cell death, the concept of the abscopal effect, the importance of the cGAS STING pathway, and their relevance in the context of the tumour microenvironment." (PMID 33499003, 2021). "The cGAS/STING signaling pathway is generally thought to mitigate tumorigenesis, and administration of STING agonists has been shown to significantly inhibit tumor development in animal studies via diverse mechanisms." (PMID 34768716, 2021). "TREX1 and cGAS-STING have been proposed to function in the tumor microenvironment, where TREX1 is believed to degrade tumor-derived DNA that would otherwise stimulate the cGAS-STING pathway and elicit antitumor immunity." (PMID 33868310, 2021). "We utilized RNA sequencing and clinical data of OSCC patients from the TCGA database to investigate the correlation between cGAS-STING signaling pathway and the tumor immune microenvironment." (PMID 34625078, 2021). "Our current findings further suggest an additional benefit of cGAS-STING-IRF3 axis activation owing to increased expression of the CXCL10 and CCL5 chemokines, leading to T cell tumor infiltration." (PMID 34488791, 2021). "However, cGAS deficiency in cGAMP unresponsive cancer cells did not enable cells to respond to STING agonists showing that STING dysfunction is not maintained by cGAS overstimulation in the tested tumor cells." (PMID 33790360, 2021).